IL6 (interleukin 6)
Diseases named in the same sentence as IL6 in open-access papers (continued):
Sharing a sentence is not in itself a finding about the gene and the disease.
COVID-19 (continued). "Similarly, serum IL-6, CXCL8, TNFα levels were increased in hospitalized COVID-19 patients (n = 1484) compared to non-infected by SARS-CoV-2 (n = 257) and serum levels of these pro-inflammatory mediators were positively correlated with mortality." (PMID 36941580, 2023). "However, the studies mentioned have not indicated the correlation between IL-6 and GSH levels in COVID-19 specifically." (PMID 37005767, 2023). "There is also a hypothesis that beta-blockers, unlike RAAS blockers, may improve outcomes in COVID-19 patients, as they were found to reduce the expression of ACE2 receptors and interleukin-6." (PMID 36732874, 2023). "In addition, procalcitonin, IL-6, IL1B, INF γ, IP10, and MCP1 serum, and LDH, which were reported earlier as significant predictors for the severity of COVID-19 were not investigated in the current study." (PMID 38130539, 2023). "Although the IL6 gene is not among the top 20 DEGs, it is noteworthy that it is over-expressed downstream to several signaling pathways, like TNF, IL17, C-type lectin receptors, and COVID-19 disease KEGG pathways." (PMID 38003837, 2023). "Mechanically ventilated COVID-19 patients with and without SSC-CIP had comparable initial inflammation levels on admission, as indicated by C-reactive protein (CRP), procalcitonin (PCT), interleukin-6 (IL-6), and ferritin." (PMID 37119516, 2023). "In the COVID-19 patients, the plasma sCD137 did not correlate with CRP (r = −0.231, p = 0.289), procalcitonin (r = 0.129, p = 0.559), ferritin (r = 0.208, p = 0.341), or IL-6 (r = −0.122, p = 0.600)." (PMID 38139346, 2023). "In this prospective study including COVID-19 patients with or without CKD at baseline, we assessed the incremental values of the blood biomarkers (IL-6 and SAA) and evaluated them at hospitalization to identify if they could predict fatal outcome and AKI." (PMID 38203482, 2023). "However, IL-6 and TNF-α, but not testosterone and inhibin B are connected to older age in COVID-19 patients." (PMID 36381078, 2022). "Although serum proinflammatory cytokines (IL6, IL18) were detected in severe cases, we did not observe differences after comparing patients with mild/moderate and severe cases of COVID-19 in multivariate analysis, suggesting that differences do not persist after recovery." (PMID 35172279, 2022). "Moreover, only IL-6 and MPO remained significantly different between the severe COVID-19 and severe negative groups during the course of illness." (PMID 35453080, 2022). "In addition, blood tests did not include inflammatory biomarkers such as IL-6 and TNF-alfa, not assessed for the routinely evaluation of COVID-19 patients at our Center." (PMID 36090992, 2022). "In a different way, whereas IFN-α showed a positive correlation with IL-6 in the control group without SIgA, the IFN-α showed a positive correlation with IL-10 in the control group with SIgA, with IFN-γ in the COVID-19 group with SIgA, and with IL-13 in both COVID-19 groups." (PMID 35686128, 2022). "We not only confirmed the predictive value of high WBC count and neutrophilia for COVID-19 mortality and VS need, but in patients with unfavourable outcomes we also found increased levels of two other markers of inflammation rather than CRP: ferritin and IL-6." (PMID 35584141, 2022). "In addition to IL-6, the serum levels of IL-2R, IL-10, IL-1β, IL-4, IL-8, IL-17 and TNF-α were also elevated in both severe and non-surviving COVID-19 patients." (PMID 35237162, 2022). "That upon normalization with GAPDH both IL-6 and NRF2 showed massive induction (>400-fold) in the case of patients with mild infection and in pre- and post-CAM patients reinforces the idea that GAPDH is not a suitable reference gene for the COVID-19 spectrum." (PMID 36377893, 2022). "Furthermore, the heatmap analysis derived from the expression pattern of hsa_circ_0000479/hsa-miR-149-5p/IL-6, RIG-I axis reveals a distinctive expression profile between COVID-19 samples and negative controls." (PMID 36081604, 2022).
COVID-19 (continued). "We hypothesize that the pro-inflammatory effect of Lp(a) on endothelial cells in COVID-19 patients may be local and connected with atherogenesis, and therefore may not be manifested in CRP or IL-6 serum concentration." (PMID 35675355, 2022). "However, in the plasma of SARS-CoV-2-infected patients we found increased levels of both axes, IL-6/CRP and IL-18/ferritin; however, although IL-6 positively correlated with CRP, IL-18 failed to correlate with ferritin in COVID-19 patients." (PMID 35663992, 2022). "Notably, children and adults exhibit differential inflammatory responses during primary COVID-19, with adults demonstrating higher levels of LBP and IL-6, while healthy adult and pediatric controls were not significantly different in these markers." (PMID 36032119, 2022). "In the same way, COVID-19 patients with serum LDH levels > 550 U/L, ferritin levels > 1600–2000 ng/mL, and D-dimer levels > 3000–5000 ng/mL represent critically ill patients who would not respond to anti-IL-6 treatments." (PMID 35645219, 2022). "Risk factors related to progression were reported in nonsevere COVID-19 patients, such as lymphocyte count, neutrophil count, CD4+ and CD8+ T cell counts, CRP, D-dimer, interleukin-6, interleukin-8, lactate dehydrogenase, age, dyspnoea on admission, and hypertension." (PMID 35619076, 2022). "After stimulation with human rIL6, there was no significant increase in IL-1β, IL-6 or IFN-γ lymphocyte or monocyte producers, suggesting that human rIL-6 in COVID-19 patients may not induce the synthesis of proinflammatory cytokines by circulating leucocytes." (PMID 35901034, 2022). "Furthermore, prognostic biochemical markers in COVID-19 including the inflammatory cytokines C-reactive protein (CRP), interleukin-6, and interleukin-10, were not measured due to limited resources." (PMID 33781275, 2021). "In our cohort, similar to previous studies, higher levels of IL-6, CRP, LDH, D-dimer, and troponin were found in non-survivors compared to survivors, further supporting the hypothesis of microvascular COVID-19 lung thrombo-inflammatory syndrome." (PMID 33355697, 2021). "Moreover, serum levels of IL-6, IL-8, IL-10 and CRP were higher in severe COVID-19 patients compared to non-severe patients." (PMID 34603318, 2021). "No statistical significance could be observed between COVID-19 patients with and without CAPA except for Interleukin-6 (median 259, range 28–793 versus median 118, range 12–234; p = 0.013)." (PMID 33730058, 2021). "This phenomenon suggested the decrease of T-cells in COVID-19 patients may be due to the negative effects of high serum concentrations of TNF-α, IL-6, IL-10 on the survival or proliferation of T-cells." (PMID 33435865, 2021). "Higher ferritin levels in COVID-19 are not exclusively driven by SARS-CoV-2 infection; it may also occur due to other inflammatory diseases or several inflammatory cytokines such as IL-6." (PMID 34538093, 2021). "None of the models proposed by us to differentiate between men with COVID-19 and men without COVID-19 found cytokines/chemokines as important features, while in women, SVM identified IP-10 and IL-6 as important features to discriminate between those with COVID-19 and those without." (PMID 34943434, 2021). "Volunteers with self-reported neurological problems (nCoV, n = 8) had a positive correlation of IL6 with age or severity of the sequalae, at least one co-morbidity and increased SARS-CoV-2 antibody compared to those COVID-19 individuals without neurological issues (CoV, n = 16)." (PMID 33668514, 2021). "As expected, the more severe COVID-19 patients demonstrated sustained high levels of proinflammatory cytokines/chemokines compared with the non-ICU patients, that reached statistical significance for IL-6 and IL-8, as reported by others." (PMID 33619281, 2021).
COVID-19 (continued). "Another monoclonal antibody belonging to anti-IL-6 drug class, siltuximab, currently approved in multicentric Castleman disease with HIV-negative and human herpesvirus-8 negative, is under investigation for ARDS in COVID-19 patients." (PMID 32527304, 2020). "This research has found flow cytometric profiles of increased IL-6, granulocyte-macrophage colony stimulating factor (GM-CSF), and IFN-γ in these severe patients, whereas TNF-α was not significantly up-regulated in CD4+ T cells from COVID-19 patients." (PMID 32350134, 2020). "In our study, we first showed that despite similar respiratory severity, plasma concentrations of numerous cytokines characterizing the “cytokine storm” (i.e. IL-1β, IL-6, IL-8, IL-15, TNF-α, CCL2, CCL4, CCL19, CCL20, TGF-α) were lower in COVID-19 compared to non-COVID-19 patients." (PMID 33272291, 2020). "Cox regression analysis including the parameters differed between patients with pneumonia and those without indicated that older age and circulating levels of IL-6, CRP, procalcitonin, and lactate at the 1st day after admission to hospital significantly predicted the progression of COVID-19." (PMID 33239109, 2020). "Levels of serum IL-10 (p = 0.0001), IL-6 (p = 0.002), MIP-3α (p = 0.02) and CD40-L levels (p = 0.002) significantly increased from 5 to 9 day of illness to 10–21 day of illness in patients with moderate-to-severe COVID-19, but not in those with mild illness." (PMID 33199778, 2020). "Furthermore, NIH does not recommend either for or against the use of COVID-19 convalescent plasma, SARS-CoV-2 immune globulin or Interleukin-6 inhibitors (e.g., sarilumab, siltuximab, tocilizumab) for the treatment of COVID-19, due to insufficient data." (PMID 32756480, 2020). "Serum inflammatory factor levels of IL-2, IL-1β, IL-5, IL-4, IL-6, IL-8, IL-10, IL-17, IL-12P70, IFN-α, TNF-α, IFN-γ, endotoxin, CRP, and hs-CRP of non-severe COVID-19 patients across different age groups (< 50, 50–60, 60–70, and ≥ 70 years) were not significantly different." (PMID 33065551, 2020). "However, specific analytical parameters, including ALT, GGT, troponin I, and IL-6 in non-COVID-19 patients, and ALT, troponin I, and platelets in COVID-19 patients, may demonstrate significant interrelationships." (PMID 40364223, 2025). "However, by using COVID-19 cohort samples, we demonstrated that non-heat-inactivated serum from mild and severe COVID-19 patients similarly suppressed IFNβ, ISG IRF7, and cytokine IL-6 induced by complement-opsonized SARS-CoV-2." (PMID 38418557, 2024). "Another study that compared PCC patients with patients who had COVID-19 but did not present PCC, and patients who had PCC and recovered, showed that ongoing PCC could be characterised by higher circulating IL-1β, IL-6 and TNFα, 8 to 10 months after acute infection." (PMID 38549752, 2024). "Both were elevated in COVID-19 positive and COVID-19 negative sepsis patients, supporting previous findings by Traby and co-workers, who reported elevated levels of citrullinated histone H3, D-dimer, CRP, IL-6, as well as an increased neutrophil-to-lymphocyte ratio in COVID-19 patients." (PMID 36980378, 2023). "Although the risk of nosocomial infection was not high in clinical trials in COVID-19 (<1% in both REMAP-CAP and RECOVERY;), careful evaluation of the potential harms of IL6RA in a population with infection will be required in trial design, given the double-edged nature of IL6 inhibition." (PMID 36716318, 2023). "Very recently, a cohort study showed that acute COVID-19 or postacute sequelae of COVID-19 (PASC) are not related to autoantibodies but to elevated plasma levels of proinflammatory cytokines such as interleukin-1 beta (IL-1β), IL-6, and tumor necrosis factor alpha (TNF-α)." (PMID 37095536, 2023).
COVID-19 (continued). "However, our finding that the COVID-19 group without SIgA also presented a positive correlation between IFN-γ and IL-6, two months after the SARS-CoV-2 infection, can reinforce the importance of the other features formerly described in the response necessary to guarantee SIgA production." (PMID 35686128, 2022). "In addition to IL-6, other inflammatory protein such as CRP, serum ferritin and coagulation index, and D-dimer were elevated in patients with COVID-19 and diabetes compared to those without diabetes, indicating that patients with comorbidities are more prone to an inflammatory response." (PMID 35162870, 2022). "In contrast, no mortality benefit was observed in studies using the IL-6 blocker sarilumab, which has an identical biological mechanism of action as tocilizumab (antibody that binds IL-6 receptor) (WHO Rapid Evidence Appraisal for COVID-19 Therapies (REACT) Working Group, 2021)." (PMID 35814227, 2022). "A persistent inflammatory state and immune activation, characterized by increased blood levels of the inflammatory cytokines–TNFα, IL-6, IL-1 and CRP, although not specific to COVID-19, may induce apoptosis with secondary endothelial dysfunction and may increase intrahepatic clot development risk." (PMID 36556915, 2022). "Thus, several biomarkers that have been associated with clinical myocarditis were found to occur in a majority of COVID-19 patients without a history of CVD that are under 50 years of age including troponin T, CRP, IL-6, CK-MB, D-dimer and kappa and lambda immunoglobulin FLCs." (PMID 36292038, 2022). "After adjustment for age, BMI, CCI score, and multiple testing, men with severe COVID-19 had higher median (IQR) concentrations of serum IL-6 (61 pg/mL vs 26 pg/mL; P = .003) and hepatocyte growth factor (HGF; 994 [383-2308] pg/mL vs 330 pg/mL; P = .002) compared with men without severe COVID-19." (PMID 34032853, 2021). "In addition, we found that calcium levels are reduced in severe COVID-19 patients, and this parameter showed strong negative correlations with MCP-1, IL-18, IL-8, IL-6, and IL-10 and positive correlation with T cell number, indicating its good prognostic factor." (PMID 33692788, 2021). "Therefore, we next examined if ATX and IL-6 serum levels correlate, to discover if, most importantly, ATX levels correlated significantly with IL-6 levels in the serum of ICU patients (not receiving Dex), suggesting a possible interplay of ATX/LPA with the cytokine storm in COVID-19." (PMID 34576169, 2021). "IL-6, when combined with SARS-CoV-2 RNAaemia rather than with other markers such as SpO2/FiO2, CRP, and LDH, may be a pathological biomarker indicating deterioration of primary COVID-19 rather than secondary inflammation." (PMID 34379684, 2021). "Compared with patients without neurological complications, those with COVID-19-related neurological complications had significantly higher neutrophil count, higher D-dimer levels, serum creatinine, troponin, procalcitonin, LDH, and interleukin-6, and lower levels of hemoglobin and lymphocyte count." (PMID 34566878, 2021). "On the other hand, IL-6 and ACE2 were found to be successful in classifying COVID-19 patients with headache (SeIL-6: 0.82; SpIL-6:0.48) (SeACE2: 0.79; SpACE2: 0.53), while NLRP3 was successful in classifying COVID-19 patients without headache (SeNLRP3: 0.38; SpNLRP3:0.93)." (PMID 34384355, 2021). "Theoretically, monitoring the IL-6 level is crucial to understanding the pathophysiological process of ARDS; however, whether IL-6 levels can predict the severity of pulmonary injury has not been fully investigated in patients with COVID-19." (PMID 32765283, 2020).
COVID-19 (continued). "Finally, eight COVID-19 patients not treated with EBT were also retrospectively observed as to overtime variation of the clinical and biochemical parameters (including the natural decay of IL-6 and SOFA score variation)." (PMID 33046113, 2020). "Although RIC has been shown to lower levels of IL-6, TNF-α, and IL-1β and improve survival in animal models of sepsis, whether this concept inspired by animal studies has an impact on inflammatory cytokines stimulated by COVID-19 has not been previously explored." (PMID 36445625, 2024). "Finally, laboratory studies have shown that IL-6 does not pass through the placenta; considering the low transplacental transmission of SARS-CoV-2, it can be concluded that the placental barrier effectively defends against the consequences of the COVID-19 cytokine storm in the fetus." (PMID 37515250, 2023). "Additionally, based on a meta-analysis included about 23 studies, IL-6, IL-8, IL-10, IL-2R, and TNF-α cytokine levels were significantly higher and T-lymphocyte levels were significantly lower among serum of severe cases as compared to non-severe COVID-19 patients." (PMID 35223745, 2022). "Binary regression analysis showed that elevated selectins P, E and L and VWF in COVID-19 patients at the time of hospital admission could predict future thrombosis; in contrast to TLC, NLR, lymphocytes percentage, platelets count, CRP, LDH, IL-6 and PCT that could not." (PMID 35061142, 2022). "The levels of pGSN/IP-10, pGSN/CTAK, pGSN/IL-6 and pGSN/M-CSF (but not pGSN/HGF) were elevated in patients that were discharged, suggesting that pGSN levels in combination with inflammatory cytokines especially pGSN/IL-6, may predict mild and favorable outcomes for hospitalized COVID-19 patients." (PMID 36148234, 2022). "Moreover, we characterized the dynamics of cytokine releases in severe/critical COVID-19, including the lack of IFN-α and IL-17E at the early days after disease onset, and distinct fluctuations of two groups of cytokines, respectively, represented by IL-6 at 5–20 dpi and IL-8 at 16–30 dpi." (PMID 34103487, 2021). "In addition, it has been reported that IL-6, high-density lipoprotein (HDL) cholesterol, creatinine, C-reactive protein, high-sensitivity cardiac troponin I (hs-cTnI), D-dimer levels and prothrombin time were significantly higher in the severe COVID-19 CVD group than those in the non-severe one." (PMID 34834033, 2021). "In summary, in COVID-19 patients with mild clinical symptoms, regardless of whether they were hospitalized, all eight indicators were increased within 2 weeks after infection, and the three indicators, namely, DD, FIB, and IL-6, showed the most significant increases." (PMID 34109187, 2021).